GPAA1 (glycosylphosphatidylinositol anchor attachment 1)
Description:
Component of the glycosylphosphatidylinositol-anchor (GPI-anchor) transamidase (GPI-T) complex that catalyzes the formation of the linkage between a proprotein and a GPI-anchor and participates in GPI anchored protein biosynthesis. Binds GPI-anchor.
Synonyms: hGAA1; GAA1; GPIBD15
Tractability: Small molecule: a structure with a bound ligand is known. Antibody: UniProt predicts a signal peptide or a membrane-spanning region. PROTAC: ubiquitination databases record sites on it; its protein half-life has been measured.
Gene: Protein-coding gene on chromosome 8 (144,082,337 to 144,093,149, forward strand). Ensembl gene ENSG00000197858.
Subcellular location: Endoplasmic reticulum membrane
Subcellular location (Human Protein Atlas): Cytosol; Endoplasmic reticulum; Centrosome; Mitochondria
Pathways (Reactome):
Metabolism of proteins: Attachment of GPI anchor to uPAR
Gene Ontology:
Molecular function: GPI anchor binding; protein binding
Biological process: attachment of GPI anchor to protein; GPI anchored protein biosynthesis; protein retention in ER lumen; GPI anchor biosynthetic process
Cellular component: endoplasmic reticulum; endoplasmic reticulum membrane; GPI-anchor transamidase complex; membrane
Genetic constraint (gnomAD): Loss-of-function variants: 51 observed, 59.79 expected, observed/expected ratio (o/e) 0.85, 90% interval 0.68 to 1.08. The upper end of that interval is the gene's LOEUF score, 1.08, which puts it in group 4 of 6, group 1 being the genes least tolerant of losing a copy. Missense variants: 770 observed, 803.12 expected, observed/expected ratio (o/e) 0.96, 90% interval 0.9 to 1.02. Synonymous variants: 393 observed, 365.35 expected, observed/expected ratio (o/e) 1.08, 90% interval 0.99 to 1.17.
Gene-disease validity (ClinGen):
ClinGen rates the evidence that GPAA1 causes each of these diseases.
glycosylphosphatidylinositol biosynthesis defect 15 (autosomal recessive): Definitive. A rare, genetic, syndromic intellectual disability characterized by global developmental delay, early-onset seizures, cerebellar atrophy, osteopenia, nystagmus and dysmorphic facial features, including bitemporal narrowing, prominent forehead, anteverted nares.
Homologues: Orthologues: chimpanzee GPAA1 (99% identical), macaque GPAA1 (99% identical), rabbit GPAA1 (94% identical), guinea pig GPAA1 (93% identical), pig GPAA1 (92% identical), mouse Gpaa1 (91% identical), rat Gpaa1 (91% identical), dog GPAA1 (89% identical), tropical clawed frog gpaa1 (66% identical), zebrafish gpaa1 (60% identical), Drosophila melanogaster GAA1 (33% identical), Caenorhabditis elegans gpaa-1 (23% identical).
Diseases named in the same sentence as GPAA1 in open-access papers:
GPAA1 is named in the same sentence as 43 diseases in open-access papers, as found by Europe PMC text mining. Sharing a sentence is not in itself a finding about the gene and the disease. The quoted sentences say what the papers report.
breast carcinoma (5 papers, 2019 to 2024). "GPAA1 has been found to be overexpressed in head and neck squamous cell carcinoma, hepatocellular carcinoma, breast carcinoma, and colorectal carcinoma." (PMID 31118109, 2019). "Moreover, gain of chromosome copy number in breast cancer results in elevated expression of transamidase subunits such as GPI anchor attachment protein 1 (GPAA1) and GPI class T (PIG-T)." (PMID 33344222, 2020). "We also found that GPAA1 and PIGU are highly amplified in breast cancer cell lines, and inhibiting the expression of PIGU has a negative impact on cell proliferation." (PMID 39015576, 2024). "Surprisingly, In multiple microscopic views, the expression of GPAA1 and PIGU in breast cancer cells was negatively correlated with the expression of CD8 molecules in neighboring lymphocytes." (PMID 39015576, 2024). "The infiltration of CD8+T cells in breast cancer exhibits a negative correlation with the expression levels of GPAA1 and PIGU." (PMID 39015576, 2024).
gastric cancer (5 papers, 2019 to 2024). A primary or metastatic malignant neoplasm involving the stomach. "For the diagnosis, upregulation of GPAA1 is closely associated with poor prognosis in gastric cancer, and its expression is positively related ERBB2." (PMID 31118109, 2019). "From these results, we can deduce that GPAA1 could be a promising diagnostic biomarker and potential therapeutic target for gastric cancer." (PMID 31118109, 2019). "To acquire further insight into whether GPAA1 could regulate cell proliferation and the cell cycle, we conducted a series gain-of-function and loss-of-function studies in gastric cancer cells." (PMID 31118109, 2019). "In the present study, we comprehensively confirmed that GPAA1 expression was extensively upregulated in malignant tumours and offered the first demonstration of the expression pattern, biological function, and underlying mechanism of GPAA1 in gastric cancer." (PMID 31118109, 2019). "GPAA1 could be a promising diagnostic biomarker and therapeutic target for gastric cancer." (PMID 31118109, 2019). "However, overexpression of GPAA1 dramatically promoted tumour growth and Akt activation, which were reversed by trastuzumab treatment, indicating the diagnostic and therapeutic potential of GPAA1 in gastric cancer." (PMID 31118109, 2019). "For bladder cancer, an upregulation of the PIG-U-subunit and downregulation of the PIG-K-subunit are described, while for gastric cancer, an upregulation of GPAA1 was described." (PMID 38893127, 2024). "For example, GPAA1 facilitates the advancement of gastric cancer by increasing the expression of GPI-anchored proteins and augmenting the ERBB signaling pathway." (PMID 39015576, 2024). "In vitro and in vivo experiments showed that GPAA1 promotes the growth and metastasis of gastric cancer." (PMID 31118109, 2019). "Western blotting, an in situ proximity ligation assay, and co-immunoprecipitation (co-IP) were performed to reveal the mechanism of GPAA1 in gastric cancer." (PMID 31118109, 2019). "The GPAA1 expression pattern in gastric cancer cells was examined by western blotting and real-time PCR, which showed that the expression of GPAA1 in AGS and SGC-7901 cells was higher than that in the other cell lines." (PMID 31118109, 2019). "Gastric cancer cells with GPAA1 knockdown exhibited significantly reduced migration and invasive abilities compared with those of control cells, consistent with the phenotype observed in GPAA1-overexpressing cells." (PMID 31118109, 2019). "In conclusion, our research showed that GPAA1 is significantly overexpressed in gastric cancer due to chromosomal amplification and performs significant functions in malignant transformation and progression, including mediation of tumour growth and metastasis." (PMID 31118109, 2019). "In summary, the GPI transamidase complex component GPAA1 was validated to be overexpressed in gastric cancer and to exert oncogenic effects, including the acceleration of proliferation and metastasis." (PMID 31118109, 2019). "Taken together, these findings indicate that GPAA1 accelerates the invasion and metastasis of gastric cancer by regulating the expression of GPI-APs, which perform crucial functions in metastasis." (PMID 31118109, 2019). "Next, we investigated the expression profile of GPAA1 in gastric cancer and the relationship between GPAA1 expression and prognosis." (PMID 31118109, 2019). "Accordingly, overexpression of GPAA1 profoundly promoted the proliferation of gastric cancer cells, an effect that was counteracted by the administration of trastuzumab, a blocker simultaneously targeting EGFR and ERBB2." (PMID 31118109, 2019). "Coincidently, the gene encoding GPAA1 is located on human chromosome 8q24, a locus with frequent copy number alteration (CNA) closely related to gastric cancer carcinogenesis." (PMID 31118109, 2019).
gastric cancer (continued). "In addition, the noticeably increased expression of GPAA1 in gastric cancer was validated through paired tumour and normal tissues obtained from a sample library established at Ren Ji Hospital, School of Medicine, Shanghai Jiao Tong University." (PMID 31118109, 2019). "Moreover, the expression of GPAA1 is independently correlated with poor survival and outcomes of gastric cancer patients." (PMID 31118109, 2019). "Moreover, the correlation between GPAA1 expression and the survival rate of gastric cancer patients was examined via the Kaplan-Meier method and log-rank tests based on several cohorts in the GEO database; higher GPAA1 expression predicted poorer survival." (PMID 31118109, 2019). "Thus, we concluded that GPAA1 is overexpressed in gastric cancer and is closely related to an unsatisfactory prognosis." (PMID 31118109, 2019). "Here, we found that GPAA1 is overexpressed in gastric cancer due to chromosomal amplification." (PMID 31118109, 2019). "Together, these results revealed that GPAA1 might be a promising biomarker and therapeutic target for gastric cancer." (PMID 31118109, 2019). "GPAA1 was a markedly upregulated oncogene in gastric cancer due to chromosomal amplification." (PMID 31118109, 2019). "Flow cytometric analysis revealed that upregulation of GPAA1 profoundly suppressed but knockdown of GPAA1 increased the proportion of cells in the G0/G1 phase, indicating that GPAA1 may stimulate the G1-to-S phase transition in stomach cancer cell." (PMID 31118109, 2019). "Thus, we speculated that GPAA1 expression is highly upregulated in gastric cancer and aimed to investigate its function and molecular mechanism." (PMID 31118109, 2019). "Then, the Kaplan-Meier method and log-rank test were used to evaluate the effects of GPAA1 and ERBB2 alone and in combination on the survival rate of gastric cancer patients." (PMID 31118109, 2019). "In summary, GPAA1 expression was highly synergistic with ERBB2 expression, and this expression was correlated with the progression of gastric cancer and predicted unsatisfactory outcomes." (PMID 31118109, 2019). "Unanswered questions remain that require further exploration of GPAA1- and GPI-AP-related enzymes and proteins in gastric cancer." (PMID 31118109, 2019). "GPAA1, as another subunit of GPI-T, was shown to be highly upregulated in gastric cancer." (PMID 38893127, 2024). "Furthermore, Lapatinib also exerted powerfully inhibitory effect on proliferation of gastric cancer cells, AGS and SGC-7901, which endogenously generate high expression of GPAA1." (PMID 31118109, 2019). "First, the expression patterns and biological functions of the GPI transamidase complex components in addition to GPAA1—PIG-T, GPI8, PIG-S, and PIG-U—are unknown in gastric cancer." (PMID 31118109, 2019). "Moreover, the results showed that GPAA1 promoted tumour growth via the enhancement of ERBB signalling, which provided a strategy of combined therapy with ERBB inhibitors or antibodies in gastric cancer." (PMID 31118109, 2019). "Therefore, we concluded that GPAA1 promotes the interaction between EGFR and ERBB2 and the signalling of the downstream promoter of proliferation—Akt—to enhance the uncontrolled growth of gastric cancer cells." (PMID 31118109, 2019).
liver cancer (3 papers, 2019 to 2021). An epithelial or non-epithelial malignant neoplasm that arises from the liver. "For example, GPI8 and GPAA1 are subunits of GPIT that demonstrate differential expression in liver cancer." (PMID 34659659, 2021). "Based on the evidence, expression changes in GPI8 and GPAA1 in liver cancer are down-regulated and up-regulated, respectively." (PMID 34659659, 2021). "We found COLEC10, GPAA1, CD5L, NCSTN, SNX27, GOLPH3L, and HIST2H2AC genes were associated with worst OS (HR < 1) in female liver cancer patients." (PMID 31216110, 2019).
Cerebellar atrophy (2 papers, 2019 to 2023). Cerebellar atrophy is defined as a cerebellum with initially normal structures, in a posterior fossa with normal size, which displays enlarged fissures (interfolial spaces) in comparison to the foliae secondary to loss of tissue. "Most recently, Nguyen and colleagues showed individuals with mutations in GPAA1, a GPI transamidase complex protein, present with developmental delay, hypotonia, early-onset seizures, cerebellar atrophy and osteopenia (MIM 617810)." (PMID 31413155, 2019). "GPAA1 defects determine a recessive disorder characterized by a complex neurological phenotype, including intellectual disability, dysarthria, nystagmus, spasticity, ataxic gait, hypotonia, seizures, and cerebellar atrophy." (PMID 37510348, 2023).
colorectal cancer (2 papers, 2019 to 2025). A primary or metastatic malignant neoplasm that affects the colon or rectum. "Glycosylphosphatidylinositol(GPI) Anchor Attachment Protein 1 (GPAA1) plays a critical role in GPI-anchor biosynthesis, yet its pan-cancer expression patterns and functional significance in Colorectal Cancer(CRC) remain unclear." (PMID 41367867, 2025).
developmental delay (2 papers, 2019 to 2025). "Biallelic variants of GPAA1, primarily missense ones, have been associated with a disorder (MIM#617810) which includes developmental delay and epilepsy as seen in our patient." (PMID 40467929, 2025).
hepatocellular carcinoma (2 papers, 2018 to 2024). A malignant tumor that arises from hepatocytes. "High expression of GPAA1 exacerbates the progression of hepatocellular carcinoma." (PMID 39015576, 2024).
lymph node metastasis (1 paper, 2025). "Given that GPAA1 expression was correlated with lymph node metastasis in CRC patients, we further explored its function in regulating the migration and invasion of CRC cells." (PMID 41367867, 2025).
melanoma (1 paper, 2020). A malignant, usually aggressive tumor composed of atypical, neoplastic melanocytes. "We constructed a 6-gene signature (IQCE, RFX6, GPAA1, BAHCC1, CLEC2B, and AGAP2) as a novel prognostic marker for predicting the survival of melanoma patients." (PMID 32462000, 2020). "In order to verify whether IQCE, RFX6, GPAA1, BAHCC1, CLEC2B, and AGAP2 were highly expressed in melanoma tissues as predicted, we experimentally confirmed this by qRT-PCR and immunohistochemical staining using melanoma tissues extracted from 10 patients." (PMID 32462000, 2020). "In addition, immunohistochemistry analysis demonstrated that IQCE, RFX6, GPAA1, BAHCC1, CLEC2B, and AGAP2 were highly expressed in melanoma tissues compared with normal tissue." (PMID 32462000, 2020).
schizophrenia (1 paper, 2019). A major psychotic disorder characterized by abnormalities in the perception or expression of reality. "GPAA1, a component of the complex that attaches GPI anchors to proteins, was normally expressed in both total homogenate and an ER-enriched fraction, suggesting that GPI attachment is intact in schizophrenia." (PMID 30664618, 2019).
Seizure (1 paper, 2023). A seizure is an intermittent abnormality of nervous system physiology characterized by a transient occurrence of signs and/or symptoms due to abnormal excessive or synchronous neuronal activity in the brain. "Seizures are very common in all the forms described, but they are more frequently controlled by medication in PIGK, GPAA1 and PIGU patients; seizures are often in-tractable, on the other hand, in the case of PIGS or PIGT variants." (PMID 37510348, 2023).
cancer (13 papers, 2012 to 2025). A tumor composed of atypical neoplastic, often pleomorphic cells that invade other tissues. "We sought to systematically explore cancer-related alterations in GPAA1 and the underlying mechanism of its upregulation in the pan-cancer landscape." (PMID 31118109, 2019). "Single-cell sequencing results indicated that high GPAA1 expression was primarily enriched in tumor cells and cancer-associated fibroblasts (CAFs), suggesting these cells might be key carriers through which GPAA1 exerts its effects." (PMID 41367867, 2025). "Immunohistochemical validation via the Human Protein Atlas (HPA) database demonstrated intermediate to high GPAA1 protein expression in most cancer types." (PMID 41367867, 2025). "A comprehensive pan-cancer investigation of GPAA1 expression revealed consistently elevated mRNA levels across multiple malignancies, with CRC exhibiting particularly prominent upregulation (p < 0.05) upon integration of TCGA and GTEx datasets." (PMID 41367867, 2025). "The pan-cancer analysis revealed that GPAA1 is consistently overexpressed across multiple malignancies, with particularly striking upregulation in CRC." (PMID 41367867, 2025). "Initially, it examined the expression profiles of GPAA1 across pan-cancers, along with its correlations with immune subtypes and signaling pathways in CRC." (PMID 41367867, 2025). "This study systematically investigates the expression patterns, biological functions, and clinical implications of GPAA1 across pan-cancers, with a specific focus on CRC." (PMID 41367867, 2025). "The heat map reveals a strong correlation between GPAA1 and immune infiltration in 32 cancer types, while PIGU exhibits a significant association with immune infiltration in 33 cancer types." (PMID 39015576, 2024). "Previous studies have shown that GPAA1 is abnormally expressed and amplified in various malignant tumors, such as liver, breast, gastric, and colorectal." (PMID 36059802, 2022). "Next, wound healing and Transwell assays were conducted to evaluate the metastatic and invasive abilities of cancer cells in vitro after altering the expression of GPAA1." (PMID 31118109, 2019). "Knockdown of GPAA1 expression significantly attenuated the proliferation of cancer cells, while GPAA1 overexpression greatly promoted growth." (PMID 31118109, 2019). "The functional impacts of increased expression levels of GPAA1 in human cancers are not well understood." (PMID 31118109, 2019). "Aberrantly upregulated GPAA1 dramatically contributed to cancer growth and metastasis in in vitro and in vivo studies." (PMID 31118109, 2019). "However, a comprehensive pan-cancer analysis of GPAA1, particularly its expression pattern, prognostic value, and mechanistic role in orchestrating the immune landscape of CRC, remains largely unexplored." (PMID 41367867, 2025). "GPAA1, PIGZ and PIGX amplifications are associated with worse prognosis at a pan-cancer level." (PMID 36009354, 2022). "However, suppressing the process of GPI-AP synthesis controlled by GPAA1 is a promising tactic in cancer therapy." (PMID 31118109, 2019). "Furthermore, the colonization of cancer cells was also positively regulated by GPAA1; GPAA1 silencing dramatically reduced the colonization ability, while GPAA1 upregulation profoundly promoted this ability." (PMID 31118109, 2019). "The observed metabolic reprogramming, particularly the enrichment of oxidative phosphorylation pathways, suggests that GPAA1 may promote a metabolic state favorable for tumor growth and survival, similar to what has been reported for other cancer-related genes." (PMID 41367867, 2025). "However, comprehensive and in-depth research is still lacking on the expression characteristics of GPAA1 in pan-cancers, its association with CRC immune subtypes and genomic instability, as well as its regulatory mechanisms on the malignant phenotype of CRC cells and anti-tumor immune responses." (PMID 41367867, 2025).
cancer (continued). "In fact, it has been shown that GPAA1 and PIGU are defined as oncogenes in a variety of cancers." (PMID 39015576, 2024). "The results showed that CERS2, VAPB, GPAA1, and ST3GAL1 were widespread CNVs in pan-cancer." (PMID 36059802, 2022). "PIGT, PIGU, GPAA1, and PIGS are overexpressed in many cancers, whereas PIGK is downregulated." (PMID 34193731, 2021). "GPAA1 facilitates the expression of cancer-related GPI-anchored proteins and supplies a more robust platform—the lipid raft—to promote EGFR-ERBB2 dimerization, which further contributes to tumour growth and metastasis and to cancer progression." (PMID 31118109, 2019). "Given that GPAA1 plays a vital role in GPI-AP synthesis, we hypothesized that GPAA1 may regulate cancer metastasis through altering the expression of specific GPI-APs." (PMID 31118109, 2019).